PTH (parathyroid hormone)
Diseases named in the same sentence as PTH in open-access papers (continued):
Sharing a sentence is not in itself a finding about the gene and the disease.
chronic kidney disease (continued). "In chronic kidney disease (CKD) patients, especially in chronic HD patients, the respiratory system is also affected because both uremia and high levels of PTH have deleterious effects on lung function." (PMID 37730530, 2023). "However, from stage 3 chronic kidney disease (CKD) onwards, the renal excretion of phosphorus decreases; subsequently, the blood concentration of phosphorus and the PTH level increase from stage 3 of CKD." (PMID 37051200, 2023). "However, the diagnosis of end stage renal disease is validated since medical reimbursement of dialysis care is applied after quarterly reporting longitudinal laboratory data (such as measurement of dialysis clearance, hemoglobin, albumin, intact-PTH data) by attending physicians." (PMID 36837885, 2023). "Chronic kidney disease-mineral and bone disease, a common complication of CKD, is shown as biochemical abnormalities of calcium, phosphate, vitamin D, parathyroid hormone (PTH), bone disorders, and calcification." (PMID 37180797, 2023). "Hyperphosphatemia is a central problem in chronic kidney disease-mineral and bone disorder (CKD-MBD); serum P, Ca, and serum PTH levels interact." (PMID 37122336, 2023). "Therefore, 2017 KDIGO Chronic Kidney Disease–Mineral and Bone Disorder (CKD-MBD) Guideline emphasizes dynamic monitoring of PTH." (PMID 36267284, 2022). "Vitamin D deficiency is widely prevalent in patients with chronic kidney disease (CKD), and contributes to abnormalities in calcium, phosphate and parathyroid hormone homeostasis with increasing recognition of its key role in the pathogenesis of CKD–mineral and bone disorder." (PMID 34449087, 2022). "Similarly, a systematic review on clinical pharmacy services in chronic kidney disease (CKD) also concluded that the pharmacist interventions led to improvement in creatinine clearance (CrCl), parathyroid hormone (PTH) and calcium levels c in CKD patients." (PMID 35538500, 2022). "The patients mostly followed Chronic kidney disease–mineral and bone disorder (CKD–MBD) KGIDO as the mean serum phosphate was 4.8 ± 1.0 mg/dl and the mean PTH was 268 ± 170 pg/mL." (PMID 35077471, 2022). "A 62-year-old male patient with a history of renal phosphaturia and slowly progressive chronic kidney disease (CKD) G4A2H presented with fatigue and hypercalcemia (2.7 mmol/L corrected for albumin) with an elevated parathyroid hormone (507 pg/mL)." (PMID 35760966, 2022). "Expression of CYP27B2 is up and downregulated by parathormone (PTH) and fibroblast growth factor-23 (FGF-23) respectively in the context of chronic kidney disease and mineral bone disorder (CKD-MBD)." (PMID 35308556, 2022). "On the contrary, PTH, PTH-rP, angiotensin-II, IGF-1, PGE2, vitamin D, and chronic renal failure decrease its expression." (PMID 34441291, 2021). "In this study, the relationships between the plasma PTH fragments levels and heart rate variability (HRV) in stage 5 chronic kidney disease (CKD5) patients are explored." (PMID 34044733, 2021). "Moreover, PTH levels a couple of times higher than normal levels are considered necessary to maintain normal bone turnover in patients with chronic kidney disease (CKD); low bone responsiveness to PTH is also observed as CKD progresses." (PMID 34372813, 2021). "Although vitamin K antagonists, direct oral anticoagulants, warfarin, heparin, parathyroid hormone and vitamin D compounds are used in chronic kidney disease (CKD) treatment, there are still many challenges remaining for treating vascular calcification (VC) in uremic patients." (PMID 34398360, 2021). "In our study investigating the mineral metabolism in end-stage renal disease, it was revealed that the sKl, 1,25(OH)2D and Ca levels decreased and FGF23, PTH and P levels increased in haemodialysis patients." (PMID 33776565, 2021).
chronic kidney disease (continued). "A cross sectional study was carried out to analyze data from 20,494 United States Veterans and verify the variability of Vitamin D (25(OH)D) and parathyroid hormone (PTH) levels across race and stage of chronic kidney disease." (PMID 33022030, 2021). "A large prospective cohort study from the Chronic Kidney Disease Outcomes and Practice Patterns Study [CKDOPPS] involving 7658 patients with CKD also identified significant variations in upper target PTH levels among nephrologists." (PMID 34170509, 2021). "Secondary hyperparathyroidism (SHPT) commonly occurs in patients with end stage renal disease (ESRD) when low calcium levels and high phosphorus levels over time stimulate increased PTH secretion." (PMID 32277134, 2020). "In patients affected with chronic kidney disease (CKD), serum PTH increases due to a complex pathophysiological mechanism involving phosphorus (P), Fibroblast Growth Factor−23 (FGF-23), vitamin D metabolites and iCa." (PMID 33348538, 2020). "FGF-23 levels increase early in the course of chronic kidney disease (CKD), and precede the rise in serum phosphate and parathyroid hormone (PTH) level." (PMID 30428848, 2018). "In CKD patients, the level of OC typically correlates very strongly with other biomarkers of the chronic kidney disease-mineral bone disorder (CKD-MBD) including phosphate and parathyroid hormone." (PMID 30103541, 2018). "Data from a Chronic Renal Insufficiency Cohort study show that the first alteration observed is elevated serum FGF23, followed be decreased serum 1,25D, elevated serum PTH, and eventually elevated serum phosphate." (PMID 30249044, 2018). "In the early stages of chronic kidney disease (CKD), serum PTH levels have already increased significantly in most patients." (PMID 28741985, 2017). "FGF23 levels are increased in patients with chronic kidney disease (CKD), particularly those on dialysis, in response to increased phosphate levels, increased PTH levels, and intervention of vitamin D." (PMID 28475601, 2017). "Multivariable analysis of the relationship between quality of life and values of vitamin D or PTH were performed, with each analysis adjusted for age, sex, BMI, current smoking status, COPD severity, diabetes, hypertension, and chronic kidney disease." (PMID 26398210, 2015). "Additionally, we reported the rate of phosphorus and parathyroid hormone (PTH) monitoring recommended for chronic kidney disease (CKD) patients." (PMID 25117447, 2014). "Fibroblast growth factor-23 (FGF-23) is a phosphaturic hormone that increases in early chronic kidney disease (CKD) before abnormalities in serum calcium, phosphate, or parathyroid hormone (PTH) become apparent." (PMID 23413976, 2013). "It was suggested that in patients with chronic renal failure, the presence of high circulating levels of non-1–84 PTH fragments (most likely 7–84 PTH) detected by the second generation assay and the antagonistic effects of 7–84 PTH on the biological activity of 1–84 PTH may explain this." (PMID 22792251, 2012). "Additionally, high extracellular phosphate levels can disrupt calcium homeostasis through the systemic interactions of hormones such as fibroblast growth factor 23 (FGF23), vitamin D and parathyroid hormone (PTH), especially under pathological conditions such as chronic kidney disease (CKD)." (PMID 42193909, 2026). "Patients with chronic kidney disease (CKD) often experience mineral and bone disorders, which include abnormalities in serum calcium, phosphorus, and parathyroid hormone (PTH) levels and vitamin D metabolism as well as disturbances in bone turnover and mineralization." (PMID 40599806, 2025). "Chronic high phosphorus intake imposed a burden of renal excretion, inducing chronic kidney disease (CKD), which, in calcium and phosphorus metabolism, inhibits testosterone synthesis, stimulates the secretion of parathyroid hormone, and interferes with the synthesis of reproductive hormones." (PMID 41169787, 2025).
chronic kidney disease (continued). "Inhibitors of NaPis elicit phosphaturia and may reduce levels of PTH and FGF23 in chronic kidney disease (CKD) models." (PMID 40357590, 2025). "In end stage renal disease (ESRD) patients; excretion of phosphorus, diminished metabolism of vitamin D3, reduced calcium level, elevated PTH, chronic acidosis, old age, increased presence of diabetes as a causative factor and impaired nutritional intake are proposed to be reasons of bone illness." (PMID 40251505, 2025). "FGF23 is a negative regulator of PTH mRNA expression and secretion and can be stimulated by non-oxidized PTH, particularly in the context of chronic kidney disease (CKD)." (PMID 38732094, 2024). "Studies were conducted in rats with chronic renal failure fed normal or high phosphorus diets for 18 weeks, with and without control of circulating parathormone (PTH) levels, resulting in different degrees of aortic calcification." (PMID 38891922, 2024). "This knowledge is reflected by the current chronic kidney disease-mineral and bone disorder treatment guidelines that recommend titrating PTH within a certain range (2–9× ULN), thereby avoiding excessively high or low PTH levels." (PMID 38919277, 2024). "Notwithstanding, the intricate interplay among FGF23, parathyroid hormone, and 1α,25-dihydroxy-vitamin D holds significance in the context of a pathological condition known as mineral and bone disorder, which occurs in individuals with chronic kidney disease (CKD-MBD)." (PMID 38970663, 2024). "As a consequence of this, from the early stages of chronic kidney disease (CKD), parathyroid hormone (PTH) and fibroblast growth factor 23 (FGF-23), two hormones with phosphaturic activity, are over-secreted with the aim to regulate the serum concentration of this ion." (PMID 39407717, 2024). "The development of mineral bone disease (MBD) is a critical issue in the chronic kidney disease (CKD) context, manifesting with an abnormal metabolism of calcium, phosphorus, parathyroid hormone (PTH), and vitamin D, impairment in bone metabolism, and soft-tissue calcifications." (PMID 39202706, 2024). "Mineral and bone disorder (MBD) in chronic kidney disease (CKD) comprises abnormalities in mineral metabolites and hormones, including serum calcium, phosphate, fibroblast growth factor-23, and parathyroid hormone (PTH), as well as bone disorder and vascular calcification." (PMID 38820324, 2024). "Chronic kidney disease-mineral and bone disorder, previously known as renal osteodystrophy, is a well-known complication of CKD and is characterized by altered metabolism of calcium, phosphate, parathyroid hormone (PTH), and vitamin D." (PMID 39606517, 2024). "Moreover, there are several studies on the role of parathormone (PTH), closely interconnected with vitamin D, in the pathogenesis of restless leg syndrome (RLS) in other disease models, such as end-stage renal disease." (PMID 36873448, 2023). "Moreover, the present iron deficiency (either true or functional) with anemia or EPO administration, contributes to high iFGF23 levels, that influence phosphate, PTH, and vitamin D metabolism defined as chronic kidney disease-mineral and bone disorder (CKD-MBD)." (PMID 36831276, 2023). "A meta-analysis found that oral magnesium supplementation alone in hemodialysis (HD) patients improved chronic kidney disease-mineral-bone disease (CKD-MBD) by modulating serum Ca and parathyroid hormone (PTH) metabolism and improving carotid intima-media thickness reduction." (PMID 36837924, 2023). "Current clinical practice guidelines for the diagnosis, evaluation, prevention, and treatment of chronic kidney disease-mineral and bone disorders state that the PTH target range in non-dialysis CKD patients is not known." (PMID 36480088, 2023).
chronic kidney disease (continued). "And in a study of 909 men without known chronic kidney disease and when not taking antidiabetic medications, it was found that a high 1,25(OH)2D/25(OH)D ratio was significantly correlated with higher levels of PTH than the level of 1,25(OH)2D alone." (PMID 37324252, 2023). "The 2017 Kidney Disease: Improving Global Outcomes (KDIGO) guideline on the management of chronic kidney disease-mineral bone disorder (CKD-MBD) suggests measuring serum calcium and serum phosphate every one to three months and serum parathyroid hormone (PTH) every three to six months." (PMID 36303122, 2022). "In an animal study of cats with chronic kidney disease, a negative association between serum magnesium concentration and FGF23 was found, which was independent of calcium, phosphate, and PTH." (PMID 35629904, 2022). "Recent basic and clinical studies demonstrate that chronic kidney disease–mineral and bone disorder (CKD–MBD) directly induces inflammation and PEW, and high circulating levels of parathyroid hormone (PTH) have been proven to induce the inflammatory response that leads to PEW." (PMID 36562038, 2022). "Our observation that increased PTH levels correlates with reduced kidney function in AIP fits with a recent review describing a non-direct link between chronic kidney diseases and periodontitis." (PMID 36013449, 2022). "In patients with chronic kidney disease G3a–G5 not on dialysis, the optimal intact PTH level is not known." (PMID 34616449, 2021). "This homeostasis is disrupted in patients with chronic kidney disease (CKD) due to disruption of normal homeostatic loops with kidney function decline, with compensatory changes in several hormones (parathyroid hormone - PTH, vitamin D, fibroblast growth factor 23 - FGF23)." (PMID 33107900, 2021). "There is a negative correlation between serum SOST and PTH in patients with end-stage renal disease, and PTH can be used as a regulation of serum SOST." (PMID 34901023, 2021). "PTH concentrations are routinely measured in the diagnosis and management of bone and mineral disease and chronic kidney disease (CKD); however, the target range for PTH may vary significantly depending on vitamin D status, defined as the sum of 25(OH)D2 and 25(OH)D3 circulating levels." (PMID 31273631, 2019). "Another study also had found that a huge proportion of circulating PTH was oxidized and thus not biologically active by using sensitive mass spectroscopy approaches to measure nonoxidized PTH in 1564 patients with chronic renal failure." (PMID 30627584, 2018). "Low dietary calcium, skeletal muscle wasting, primary or secondary hyperthyroidism, chronic kidney disease (CKD), or inadequate vitamin D status may be independent contributors to high serum PTH concentrations." (PMID 28272298, 2017). "The term “chronic kidney disease-mineral bone disorder (CKD-MBD)” replaced the older term “renal osteodystrophy” to more clearly convey the broad spectrum of sequelae that accompany abnormalities in blood levels of parathyroid hormone (PTH), calcium, and phosphate, the biochemical hallmarks of SHPT." (PMID 27814753, 2016). "Finally, in patients with chronic kidney disease (CKD) the positive effects of vitamin D on erythropoiesis could also be related to its suppressive effects on PTH, which directly inhibits erythroid progenitors, EPO synthesis, and red blood cells survival." (PMID 25781618, 2015). "KDIGO Clinical Practice Guidelines for the Care of Kidney Transplant Recipients recommend treating disturbances of calcium, phosphate, and PTH as in nontransplant patients with chronic kidney disease, which are, however, not applicable for several reasons." (PMID 25861621, 2015). "Whether the association between PTH and hemoglobin exists in patients with chronic kidney disease not on dialysis (CKD-patients) has been little evaluated." (PMID 25113067, 2015).
chronic kidney disease (continued). "Blacks have high rates of chronic kidney disease, are overrepresented among the US dialysis patients, have higher parathyroid hormone levels, but greater survival compared to nonblacks." (PMID 20614473, 2010). "However, when there is a disruption in the body's calcium-phosphorus balance, such as in cases of chronic kidney disease (CKD) or other related disorders, the parathyroid gland compensates by increasing PTH secretion, a condition known as secondary hyperparathyroidism (SHPT)." (PMID 40951895, 2025). "Chronic kidney disease–mineral and bone disorder (CKD-MBD) is defined by abnormalities in calcium, phosphorus, parathyroid hormone (PTH), and vitamin D metabolism, along with bone pathology and soft tissue calcification." (PMID 41157262, 2025). "Diagnostic values of serum calcium-phosphorus product (Ca × P), PTH, vitamin K2 and their combine test for coronary artery calcification (CAC) in chronic kidney disease (CKD) patients." (PMID 41565306, 2025). "Nonetheless, treatment decisions should be guided by the presence of chronic kidney disease-mineral and bone disorder (CKD-MBD), as indicated by abnormal calcium, phosphate, PTH, alkaline phosphatase, or calcifediol levels." (PMID 41281140, 2025). "In healthy people, plasma phosphate (P), 1,25-dihydroxyvitamin D (1,25(OH)2D) and PTH are the main regulators of plasma FGF23, but from early stages of chronic kidney disease (CKD), FGF23 increases before an increase in plasma P is observed." (PMID 38770543, 2024). "Chronic kidney disease (CKD) mineral and bone disorder (MBD) comprises a triad of biochemical abnormalities (of calcium, phosphate, parathyroid hormone and vitamin D), bone abnormalities (turnover, mineralization and growth) and extra-skeletal calcification." (PMID 37624528, 2024). "BMI: body mass index; 25(OH)D: 25 hydroxyvitamin D; CKD: chronic kidney disease; PTH: parathyroid hormone; Ph: serum phosphate." (PMID 37351236, 2023). "Therefore, the decreased level of iFGF23 in INHD was not related to the difference in active vitamin D. PTH is another potential regulator of FGF23 in chronic renal failure since PTH and FGF23 were both elevated at the same time." (PMID 35801203, 2022). "According to the Clinical Practice Guidelines for Chronic Kidney Disease-Mineral and Bone Disorder (CKD-MBD) provided by the KDIGO, 37.35%, 44.58%, and 78.31% of the patients showed abnormalities in Ca, P, and PTH levels, respectively." (PMID 36309659, 2022). "The serum 24,25OH2D level was lower in adult patients with chronic kidney disease, which was suggestive of decreases in vitamin D catabolism and VDR activity, and reduced 1,25OH2D production, the level of which better correlated with the serum PTH level than did either the 25OHD or 1,25OH2D level." (PMID 34648586, 2021). "The term “chronic kidney disease-mineral bone disorder” (CKD-MBD) has been used in humans and animals to describe a condition characterized by renal osteodystrophy and abnormal mineral metabolism with high levels of serum phosphate, fibroblast growth factor (FGF)-23, and parathyroid hormone (PTH)." (PMID 32677951, 2020). "Mineral and bone disorder in chronic kidney disease (CKD-MBD) is a triad of biochemical imbalances of calcium, phosphate, parathyroid hormone and vitamin D, bone abnormalities and soft tissue calcification." (PMID 31240395, 2020). "This was explained by the hypothesis that, in the absence of chronic renal failure, PTH exerts its cardiac actions via PTH receptors found in myocardium." (PMID 28115793, 2017). "Prior to the availability of commercial intact parathyroid hormone (PTH) assays, serum total alkaline phosphatase (TAP) measurements were used as one of the surrogate markers of high bone turnover that was utilized in the management of chronic kidney disease mineral and bone disorder (CKD-MBD)." (PMID 28168054, 2017).